CRBN (cereblon)
Description:
Substrate recognition component of a DCX (DDB1-CUL4-X-box) E3 protein ligase complex that mediates the ubiquitination and subsequent proteasomal degradation of target proteins, such as MEIS2, ILF2 or GLUL. Normal degradation of key regulatory proteins is required for normal limb outgrowth and expression of the fibroblast growth factor FGF8. Maintains presynaptic glutamate release and consequently cognitive functions, such as memory and learning, by negatively regulating large-conductance calcium-activated potassium (BK) channels in excitatory neurons. Likely to function by regulating the assembly and neuronal surface expression of BK channels via its interaction with KCNT1. May also be involved in regulating anxiety-like behaviors via a BK channel-independent mechanism (By similarity). Plays a negative role in TLR4 signaling by interacting with TRAF6 and ECSIT, leading to inhibition of ECSIT ubiquitination, an important step of the signaling.
Synonyms: MRT2; MRT2A
Tractability: Small molecule: an approved drug acts on it; a structure with a bound ligand is known; a high-quality ligand is known. Antibody: UniProt places it where antibodies can reach, with medium confidence. PROTAC: it is named in the literature on targeted protein degradation; UniProt records ubiquitination sites on it; ubiquitination databases record sites on it; its protein half-life has been measured; a small molecule that binds it is known.
Chemical probes: CRBN-6-5-5-VHL (high quality), Iberdomide, MEZIGDOMIDE (high quality)
Gene: Protein-coding gene on chromosome 3 (3,144,628 to 3,179,727, reverse strand). Ensembl gene ENSG00000113851.
Subcellular location: Cytoplasm; Nucleus; Membrane
Pathways (Reactome):
Disease: Potential therapeutics for SARS
Gene Ontology:
Molecular function: protein binding; transmembrane transporter binding
Biological process: positive regulation of Wnt signaling pathway; proteasome-mediated ubiquitin-dependent protein catabolic process; protein ubiquitination; limb development; locomotory exploration behavior; negative regulation of monoatomic ion transmembrane transport; negative regulation of protein-containing complex assembly; positive regulation of protein-containing complex assembly
Cellular component: Cul4A-RING E3 ubiquitin ligase complex; cytoplasm; nucleus; Cul4B-RING E3 ubiquitin ligase complex; cytosol; membrane; perinuclear region of cytoplasm
Genetic constraint (gnomAD): Loss-of-function variants: 34 observed, 39.48 expected, observed/expected ratio (o/e) 0.86, 90% interval 0.65 to 1.15. The upper end of that interval is the gene's LOEUF score, 1.15, which puts it in group 5 of 6, group 1 being the genes least tolerant of losing a copy. Missense variants: 456 observed, 405.35 expected, observed/expected ratio (o/e) 1.12, 90% interval 1.04 to 1.22. Synonymous variants: 165 observed, 141.27 expected, observed/expected ratio (o/e) 1.17, 90% interval 1.03 to 1.33.
Gene-disease validity (ClinGen):
ClinGen rates the evidence that CRBN causes each of these diseases.
intellectual disability (autosomal recessive): Moderate.
Homologues: Orthologues: chimpanzee CRBN (99% identical), macaque CRBN (99% identical), dog CRBN (97% identical), pig CRBN (97% identical), guinea pig CRBN (96% identical), mouse Crbn (96% identical), rat Crbn (96% identical), rabbit CRBN (89% identical), zebrafish crbn (69% identical), tropical clawed frog crbn (68% identical), Drosophila melanogaster ohgt (27% identical), Caenorhabditis elegans M18.6 (22% identical).
Diseases named in the same sentence as CRBN in open-access papers:
CRBN is named in the same sentence as 118 diseases in open-access papers, as found by Europe PMC text mining. Sharing a sentence is not in itself a finding about the gene and the disease. The quoted sentences say what the papers report.
myeloma (122 papers, 2014 to 2026). "For instance, genetic mutations in CRBN have rendered lenalidomide-derived PROTACs ineffective in myeloma, highlighting the risks of single E3 dependency." (PMID 40866949, 2025). "Originally developed as a sedative, it demonstrated profound antitumor activity in multiple myeloma once its mechanism of action was linked to cereblon (CRBN), a substrate receptor of the CRL4 ubiquitin ligase complex." (PMID 41463612, 2025). "This limitation presents multiple challenges for the clinical application of PROTACs, including drug resistance due to CRBN mutations in multiple myeloma and treatment failure resulting from VHL dysfunction in clear cell renal carcinoma." (PMID 40866949, 2025). "For example, multiple CRBN mutations were found to be associated with acquired resistance to lenalidomide or pomalidomide in multiple myeloma." (PMID 38265263, 2024). "Inactivating mutations in CRBN, including missense mutations within the drug-binding domain and surrounding surfaces, have been identified in many patients with myeloma treated with thalidomide analogs." (PMID 38165043, 2024). "Some showed that the higher CRBN gene expression is associated with improved clinical responses in patients with multiple myeloma receiving IMiD-based treatments." (PMID 34336672, 2021). "Another study reported that higher expression of the CRBN gene is associated with better survival in multiple myeloma patients treated with thalidomide maintenance therapy." (PMID 34336672, 2021). "Prolonged in vitro exposure to increasing concentrations of lenalidomide resulted in IMiD-resistant myeloma cells with reduced CRBN expression caused by deletion of one copy of CRBN." (PMID 34834536, 2021). "Conversely, the loss of CRBN protein and CRBN mRNA level led to lenalidomide resistance in myeloma cells and a poor outcome in MM patients." (PMID 34207079, 2021). "CRBN dysregulation has been linked to several human diseases such as teratogenicity, leukemia, myeloma, mental retardation, and organ failure." (PMID 33916291, 2021). "The neomorphic E3 ligase activity of CRL4CRBN is induced by the binding of IMiDs to CRBN, and CRBN deficiency in a human multiple myeloma cell line confers resistance to IMiDs8,9,15." (PMID 32929090, 2020). "Although the molecular mechanisms underlying the anti-myeloma activity of IMiDsR have been reported to involve the Cullin 4A (CUL4A)- Cereblon (CRBN) E3 ligase complex mediated proteasomal degradation of downstream targets." (PMID 33014791, 2020). "Low CRBN expression is associated with the Len resistance of myeloma cells, suggesting that high CRBN protein level is required for the anti-myeloma activity of IMiDs." (PMID 33392195, 2020). "The cellular signaling programs responsible for CRBN-IMiD-mediated myeloma cytotoxicity are associated with upregulation of the interferon signaling pathway." (PMID 30760870, 2019). "Recently, studies found the level of CRBN in myeloma cells was associated with better treatment response in IMiDs (thalidomide, lenalidomide and pomalidomide) treatment." (PMID 26460955, 2015). "CRBN is essential for the anti-myeloma activity of IMiDs and loss of this protein causes drug resistance in MM cells." (PMID 26269456, 2015). "For example, a poor response to the thalidomide-based immunomodulatory drugs (IMiDs) in multiple myeloma (MM) patients has been linked to their low expression of CRBN although higher expression of CRBN is usually found in cancer cell lines from hematological tumors compared to solid cancers." (PMID 39055890, 2024). "Finally, integration of DMS data with available clinical data suggests that functional CRBN hotspots are mutated in multiple myeloma patients relapsing from treatment with lenalidomide and pomalidomide, two CRBN-based molecular glue degraders." (PMID 36329119, 2023). "It is postulated that it may be associated with the higher expression of CRBN which characterises hyperdiploid-myeloma patients." (PMID 34207079, 2021).
myeloma (continued). "We evaluated CRBN expression in bone marrow plasma cells and analyzed whether CRBN expression was associated with multiple myeloma prognosis." (PMID 34336672, 2021). "However, more recent reports suggest that lenalidomide instead binds to CRBN to induce its E3 ligase activity, causing degradation of the Ikaros transcription factors and accounting for the anti-tumor activity in myeloma." (PMID 25469886, 2014). "It should be noted that different myeloma cell lines and primary myeloma cells may have distinct genetic backgrounds, such as mutations and expression level of genes including CRBN, CASP-8, and DDB1, which affect cell proliferation and regulate cell death pathways." (PMID 33392195, 2020). "Thalidomide and its analogs are effective agents in the clinical treatment of multiple myeloma, with CRBN recognized as their primary molecular target." (PMID 41424849, 2026). "In 2010, cereblon (CRBN) was identified as the direct protein target of thalidomide, which mediates its teratogenic and anti-myeloma effects." (PMID 41304934, 2025). "IMiDs are one of the backbone treatment options in multiple myeloma (MM), rendering CRBN an intriguing candidate for use as a biomarker in clinical settings." (PMID 40650115, 2025). "This drug induces apoptosis of myeloma cells by enhancing ubiquitination degradation of CRBN-mediated transcription factors (such as Ikaros/Aiolos)." (PMID 40534867, 2025). "For example, a phase I/II trial (NCT06050512) evaluated the efficacy of the novel E3 ubiquitin ligase Cereblon (CRBN) modulator Mezigdomide combined with isazomib and dexamethasone in the treatment of relapsed refractory multiple myeloma (RRMM)." (PMID 40534867, 2025). "As an inhibitor of SHMT2, SHIN1 disrupts the SHMT2-BRCC36 interaction, leading to increased CRBN protein stability and augmented anti-myeloma efficacy of Len." (PMID 41463377, 2025). "Recently, a review of the variable response of multiple myeloma patients to IMiDs highlighted a correlation with CRBN expression levels." (PMID 40316744, 2025). "Inhibition of cereblon expression in human multiple myeloma cell lines significantly reduces cell growth and viability." (PMID 40115011, 2025). "This indicates that CRBN expression is specifically relevant to the mechanism of action of IMiDs, which rely on CRBN to exert their anti-myeloma effects." (PMID 40650115, 2025). "Mezigomide is an oral cereblon E3 ligase modulator (CELMoD) that is under clinical investigation in patients with relapsed/refractory (RR) multiple myeloma (MM)." (PMID 38539501, 2024). "These compounds serve as molecular glues, redirecting the CRBN E3 ubiquitin ligase to degrade myeloma-dependency factors, IKZF1 and IKZF3." (PMID 38165043, 2024). "Pomalidomide is an FDA-approved drug for the treatment of multiple myeloma based on its binding to an E3 ligase component cereblon (CRBN) via its glurarimide ring." (PMID 38409444, 2024). "Genetic overexpression and CRISPR/Cas9 knockout experiments were conducted in multiple myeloma (MM) cell lines and Jurkat T cell lines to determine the roles of CRBN in RXR-agonist mediated effects." (PMID 37566072, 2023). "Our previous research showed that PPAR agonists (fenofibrate, GW501516, and troglitazone) reduced the anti-myeloma effect of lenalidomide by downregulating the transcription activity of CRBN through DNA methylation and protein degradation." (PMID 37566072, 2023). "CRBN is a direct target of immunomodulatory agents and plays a critical role in IMiD-mediated anti-myeloma activity." (PMID 37566072, 2023). "IMiDs exert anti‐myeloma action via direct binding to cereblon (CRBN), the substrate receptor of the CRL4 E3 ubiquitin ligase complex." (PMID 37581569, 2023). "In human myeloma cell lines in which CRBN gene expression was suppressed by shRNA, the antitumor effects of LEN and pomalidomide (POM) were reduced depending on their dose and the burden of CRBN gene reduction." (PMID 38004369, 2023).
myeloma (continued). "CRBN is critical in immunomodulatory agent-mediated anti-myeloma activity and there are data suggesting that the level of CRBN correlates with drug sensitivity or resistance to IMiD treatment." (PMID 37566072, 2023). "IKZF1, a driver gene in multiple myeloma and other B-cell lymphomas, is the molecular target of IMiDs (immunomodulatory drugs) including lenalidomide and pomalidomide, which facilitate CRBN-mediated degradation of the Ikaros family proteins." (PMID 36991428, 2023). "Thalidomide binds cereblon, a process that is involved in the proposed mechanism in specific cancers such as breast cancer, colon cancer, multiple myeloma, and lung cancer." (PMID 36966238, 2023). "Down-regulation of CRBN leads to drug resistance in MM cell lines and primary MM cells, while CRBN overexpression enhances sensitivity to IMiDs in myeloma cell lines." (PMID 37799465, 2023). "Although acting on the E3 ligase-related function of CRBN appears to be the main mechanism for the anti-myeloma activity of IMiDs, recent reports indicate that IMiDs also act by modulating other properties of CRBN, such as chaperone function." (PMID 36139651, 2022). "In order to optimally deploy IMiDs and their newer derivates CRBN E3 ligase modulators (CELMoDs®) into future myeloma therapeutic regimens, it is imperative to understand the mechanisms behind the inevitable emergence of IMiD resistance." (PMID 36439455, 2022). "While cereblon (CRBN) is the primary target of IMiD anti-tumor activity, others have suggested the importance of myeloma metabolism in IMiD response." (PMID 35454812, 2022). "Cereblon (CRBN) is a direct binding target of immunomodulatory drugs (IMiDs) that are commonly used to treat multiple myeloma (MM)." (PMID 36358696, 2022). "Studies have shown that deletion of the CRBN genome is the main reason for myeloma cells to develop resistance to IMiDs." (PMID 36536188, 2022). "Then, it was shown that CRBN expression was required for the anti-myeloma activity of IMiDs as CRBN knockdown leads to resistance to lenalidomide and pomalidomide in MM cell lines." (PMID 36139651, 2022). "The indispensability of CRBN for the anti-myeloma effect indicates that upregulation of CRBN can potentiate the anti-myeloma effect of lenalidomide." (PMID 35321428, 2022). "The ratio of exon 10 spliced/full-length CRBN transcripts was increased in pomalidomide-refractory compared to ND or lenalidomide-refractory patients affects lenalidomide response in myeloma cell lines." (PMID 36387095, 2022). "It is now known that IMiDs exert their anti-myeloma activity mainly by binding cereblon (CRBN), the substrate receptor protein of the CRL4 E3 ubiquitin ligase (CRL4CRBN) complex." (PMID 36139651, 2022). "Accordingly, short-term bortezomib treatment inhibited the ubiquitination-mediated degradation of CRBN in myeloma cells, thereby potentiating the anti-myeloma effect of lenalidomide." (PMID 35321428, 2022). "Cereblon was identified as the primary target of thalidomide, and cereblon knockout on myeloma cell lines leads to LEN and pomalidomide resistance." (PMID 36039651, 2022). "CC-92480 is another oral CRBN E3 ligase modulator currently under clinical investigation in patients with newly diagnosed and/or refractory/relapsed multiple myeloma (NCT03374085, NCT05552976, NCT05519085, NCT03989414, NCT05372354)." (PMID 36499765, 2022). "In contrast, PPAR antagonists (GW6471, GSK3787, and GW9662) increased CRBN expression and augmented the anti-myeloma activity of lenalidomide." (PMID 36358696, 2022). "Here, we review the ways of modulating CRL4CRBN E3 ligase activity in a CRBN-dependent manner in established and upcoming therapeutic approaches in multiple myeloma." (PMID 36139651, 2022). "CRBN is expressed in bone marrow plasma cells of multiple myeloma patients, and patients with higher CRBN expression showed favorable prognosis following IMiD-based therapy." (PMID 34336672, 2021).
myeloma (continued). "Possibly, the residual myeloma cells in MRD-positive patients on LEN maintenance therapy are resistant to LEN due to decreased CRBN burden, CRBN gene mutation, and c-MYC overexpression." (PMID 34638353, 2021). "Based on these results, we constructed a new nomogram model to predict high CRBN expression in patients with multiple myeloma." (PMID 34336672, 2021). "Based on these results, we constructed a new nomogram model to predict CRBN expression in myeloma patients." (PMID 34336672, 2021). "Recent discoveries have attributed the anti-myeloma effects and enhanced T-cell activation to the binding of IMiDs to cereblon (CRBN)." (PMID 34638271, 2021). "This study aims to develop a prediction model for CRBN expression using blood markers from multiple myeloma patients." (PMID 34336672, 2021). "The benefit of IMiD therapy related to CRBN expression in multiple myeloma patients has also been addressed in several previous studies." (PMID 34336672, 2021). "Based on these results, we constructed a new nomogram model to predict high CRBN expression and the effectiveness of IMiD therapy in multiple myeloma." (PMID 34336672, 2021). "We analyzed newly diagnosed multiple myeloma patients, measured their CRBN levels using IHC and a commercial antibody, and showed that the IMiD therapy affects patient survival in a CRBN expression-dependent manner." (PMID 34336672, 2021). "CRBN expression in myeloma is also positively correlated with the survival of thalidomide-treated patients." (PMID 33916291, 2021). "CISMs exert their anti-myeloma action via distinct and complementary pathways, such as the induction of neosubstrate degradation, the inhibition of CRBN chaperone activity, and the modulation of the response to oxidative stress." (PMID 34834536, 2021). "Ikaros and Aiolos, CRBN neosubstrates and transcription factors essential for myeloma survival, are conventionally undruggable but are now regarded as promising targets for drug development." (PMID 34764413, 2021). "Although useful in underpinning the anticancer actions of IMiDs in multiple myeloma, their binding to CRBN unpins the Achilles’ heel of this drug class, specifically the notorious teratogenic effects." (PMID 33854417, 2021). "The significance of CRBN in modulating the anti-myeloma effects of IMiDs was reported by a study in which knockdown of CRBN decreased viability of myeloma cells and induced resistance to IMiD therapy." (PMID 34336672, 2021). "Several CRBN-targeting immunomodulatory drugs have recently been shown to be effective for treating multiple myeloma." (PMID 32466489, 2020). "Cereblon is a common molecular target for these drugs, but their cereblon binding as well as their clinical effects in myeloma treatment differ." (PMID 31963193, 2020). "The data showed that z-IETD-fmk potentiated the anti-myeloma activity of Len in the mock knockdown and this effect disappeared when CRBN was knocked down." (PMID 33392195, 2020). "This indicates that CRBN is required for the enhanced anti-myeloma activity of Len upon CASP-8 inhibition." (PMID 33392195, 2020). "CSN9 signalosome inhibits SCFFbxo7-mediated CRBN degradation, thereby promoting the sensitivity of myeloma cells to IMiDs." (PMID 33392195, 2020). "Nevertheless, both mechanisms support the idea that inhibiting CASP-8 activity increases CRBN protein level and benefits to the therapeutic effect of Len for the treatment of myeloma." (PMID 33392195, 2020). "For example, lenalidomide specifically binds to CRBN and promotes CUL4-mediated degradation of transcription factors implicated in the pathogenesis of myeloma." (PMID 32466489, 2020). "On the other hand, our previous experiments detected the increase of CRBN protein level after 3 days treatment of myeloma cell lines with IMiDs." (PMID 33392195, 2020).